FANCD2 (FA complementation group D2)
Diseases named in the same sentence as FANCD2 in open-access papers (continued):
Sharing a sentence is not in itself a finding about the gene and the disease.
Fanconi anemia (continued). "We also found specific upregulation of genes of the Fanconi anemia pathway, in particular FANCM, FANCD2 and FANCI, which encode known interaction partners of BLM." (PMID 35099000, 2022). "Fanconi anemia (FA) group D2 (FANCD2) is a ferroptosis-related gene crucial for DNA damage repair and negative ferroptosis regulation." (PMID 35646059, 2022). "Another interesting finding in our cohort is the high incidence of monoallelic variants in other Fanconi anemia (FA) genes: FANCA, FANCC, FANCD2, RAD51C, FANCG and FANCI." (PMID 36290365, 2022). "In parallel to its role in the process of TLS, USP1 participates in the Fanconi anemia pathway through monodeubiquitination of FANCD2 during DNA interstrand crosslink lesion repair." (PMID 35432321, 2022). "As a Fanconi anemia-associated protein, NIPA regulates the nuclear abundance of FANCD2, thereby making it essential for a functional DNA repair/Fanconi anemia/BRCA pathway." (PMID 35646639, 2022). "Deleterious alterations were also identified in nearly all (13/14) tumours in members of the Fanconi anaemia complementation groups, including FANCD2, FANCF, FANCC, FANCA, and FANCE." (PMID 34045664, 2022). "The Fanconi Anemia pathway has been well-characterized in ICL repair, however the upstream factors specific for FANCD2 localization for transcription-associated replication stress have not." (PMID 36480547, 2022). "Similar to FBXL21 ubiquitinating MYOZ1 and TCAP, another E3 ligase, the FANCL subunit of the FA (Fanconi anemia) core complex, has been shown to monoubiquitinate two interacting proteins, namely FANCD2 and FANCI." (PMID 36574402, 2022). "In detail, decreasing SERPINB3 expression reduces the USP1‐mediated deubiquitination of FANCD2–FANCI in the Fanconi anemia pathway, thereby interfering with cisplatin‐induced DNA interstrand crosslinks repair and further contributing to HNSCC cell apoptosis." (PMID 36382555, 2022). "FANCD2 (FA complementation group D2) contributes heterogeneously to Fanconi anemia (FA), a genetic disorder characterized by birth defects, progressive bone marrow failure, and cancer-prone phenotype." (PMID 35236309, 2022). "On the other hand, UBE2T is the E2 ubiquitin-conjugating enzyme for the Fanconi Anemia pathway and monoubiquitinates several proteins of the pathway, that also appeared in our screening like FANCD2 and FANCI." (PMID 33925616, 2021). "To rule out its involvement in our experimental setup, we monitored the ubiquitylation status of FANCD2, a recognized marker for activation of the Fanconi anemia pathway." (PMID 34879279, 2021). "Recruitment of the Fanconi anemia core complex to the sites of DNA damage is crucial for FANCD2 mono-ubiquitination during ICL repair." (PMID 34360546, 2021). "As a critical component of the DNA damage repair orchestra, FANCD2 functions in both the Fanconi anemia pathway that repairs inter-strand DNA crosslinks and the HR pathway that repairs DNA DSB breaks." (PMID 34206946, 2021). "Our findings showed that CHK1 phosphorylation plays a role in expression of some of the Fanconi anemia core factors and FANCD2, which is critical for ICL repair." (PMID 34360546, 2021). "FANCD2 (Fanconi anemia complementation group D2) plays a role in DNA damage repair and it is a nuclear protein and a negative mediator of the ferroptosis process." (PMID 34095228, 2021). "In COAD, we found FANCI, which plays a role in Fanconi anemia pathway, as an interacting partner of FANCD2 (down, ferroptosis negative regulator)." (PMID 33670487, 2021). "FAN1 encodes Fanconi anemia-associated nuclease 1 (FAN1), which interacts with Fanconi Anemia Complementation group D2 (FANCD2) and Fanconi Anemia Complementation group I (FANCI), forming the Fanconi Anemia core complex." (PMID 34126972, 2021). "FANCI has a key role in the Fanconi anemia DNA repair pathway, where it forms a heterodimer with FANCD2 and recruits DNA repair proteins to promote the interstrand cross-link DNA damage repair." (PMID 33868991, 2021).
Fanconi anemia (continued). "Recently it has been shown that FANCD2 can form a complex with NR2F2 or NR2C2, independently from the Fanconi anaemia (FA) core complex or monoubiquitination of FANCD2." (PMID 33244044, 2020). "Fanconi anemia (FA) components, such as FANCD2, are known to accumulate at sites of DNA replication stress and, particularly, at common fragile sites (Datta and Brosh Jr., 2019)." (PMID 33200984, 2020). "Previous studies have shown that CPT can induce DNA replication stress and activate Fanconi anemia pathway, resulting in FANCD2 monoubiquitination." (PMID 32365503, 2020). "Our work also suggests that direct modulation of FANCI phosphorylation plays a twofold role in stabilizing FANCD2 monoubiquitination, with relevance to understanding and treating both Fanconi anemia and cancer." (PMID 32117957, 2020). "FANCI:FANCD2 monoubiquitination is a critical event for replication fork stabilization by the Fanconi anemia (FA) DNA repair pathway." (PMID 32167469, 2020). "Investigation have shown that FOXM1 directly regulated the transcription of FANCD2, which is the key gene of the Fanconi anemia (FA) pathway." (PMID 32486251, 2020). "Hyperactive mTOR signaling is known to contribute to CDDP resistance, for example, by upregulating FancD2, an essential protein in the Fanconi anemia DNA repair pathway, which promotes repair of lethal CDDP-induced DNA interstrand crosslinks." (PMID 32943635, 2020). "The study also showed that FOXM1 can increase anticancer drug resistance by regulating the expression of FANCD2, which regulates the Fanconi anemia pathway and consequently increases DNA repair." (PMID 32486251, 2020). "Fanconi anaemia, complementation group D2 (FANCD2) is an important DNA damage response protein, which is activated during DNA replication as well as DNA damage repair." (PMID 32372224, 2020). "For this last aspect, celastrol promotes a reduction in cancer cells of the monoubiquitinated FANCD2 protein, promoting its degradation by the proteasome and affecting the activation of the DNA damage-induced Fanconi anemia pathway and the downstream pathways." (PMID 33330091, 2020). "An important mechanism for the removal of ICLs is the Fanconi Anemia DNA repair pathway, which is initiated by mono-ubiquitination of FANCD2 and its partner protein FANCI." (PMID 32117957, 2020). "Further studies will hopefully further clarify the exact role of FANCD2 protein after recruitment at DNA breaks during meiosis and the relationships with its mitotic function in order to provide new insight on Fanconi Anaemia pathway." (PMID 31919410, 2020). "Emerging Fanconi Anemia (FA) signaling in the field of cancer research annotates the extreme importance of its center player, Fanconi Anemia complementation group D2 (FANCD2) in protecting human cells from going awry." (PMID 33099537, 2020). "EXD2 also reportedly has a critical functional link with FANCD2, the gene responsible for Fanconi anemia." (PMID 30759165, 2019). "UAF1 activates USP1, and USP1 regulates the Fanconi Anemia repair pathway by deubiquitinating FANCD2, one of the most important players in this pathway." (PMID 31382494, 2019). "Of note, Fanconi anaemia complementation group D2 (FANCD2) as a key member within the FA, shows only basal gene expression levels in all analysed patient samples, indicating an impaired function of the FA pathway." (PMID 30700254, 2019). "FANCD2 is a DNA repair protein from the Fanconi Anemia pathway that localizes to challenged CFSs in G2 and mitosis, and is essential to ensure their efficient replication." (PMID 31180492, 2019). "The activation of this checkpoint requires the relocalization into nuclear foci and the stepwise activation of proteins of the ATR-Chk1 and the Fanconi Anemia (FA) pathways, including Topoisomerase II Binding Protein 1 (TopBP1) and FANCD2." (PMID 31320994, 2019).
Fanconi anemia (continued). "Accurate deubiquitination of the FANCD2 protein by the USP1/UAF1 complex is essential for an intact Fanconi Anemia pathway and proper DNA damage repair." (PMID 31382494, 2019). "FANCD2 gene product is an important component of the Fanconi anemia pathway of DNA damage response and acts as a recruitment factor for other DNA repair proteins." (PMID 31775835, 2019). "Activated ATR allowed the recruitment of the Fanconi anemia DNA cross-link repair pathway, evidenced by the activation of FANCD2 and its recruitment in subnuclear foci together with p-H2AX." (PMID 29559578, 2018). "Most fanconi anemia patients harbour homozygous or double heterozygous mutations in the FANCA (60-65%), FANCC (10-15%), FANCG (~10%) or FANCD2 (3-6%) genes." (PMID 29400309, 2018). "FANCD2 belongs to the Fanconi anemia pathway and is involved in the DNA damage response by cooperating with BRCA1/2 proteins in homologous-recombination (HR)-mediated repair." (PMID 30038706, 2018). "This response articulates itself on three important platforms, Replication Protein A/RPA-coated single-stranded DNA, the DNA polymerase processivity clamp PCNA and the FANCD2/I Fanconi Anemia complex." (PMID 30257459, 2018). "FANCD2 is a key component of the Fanconi Anemia repair pathway, which provides cellular resistance to DNA cross-linking agents." (PMID 30486458, 2018). "WES revealed that HMCLs displayed frequent mutations in Fanconi anemia genes (PALB2 [12%], FANCI [12%], FANCA [9%], FANCD2 [9%], BRCA2 [9%]) as well as in helicases (such as RECQL4, 15%, and BLM, 15%) and epigenetic modifiers (e.g., TET2, 15% and SETD2, 6%)." (PMID 30545397, 2018). "The recruitment of FANCD2 upon infection with pks+E. coli argues for a role of the Fanconi anemia pathway in the management of ICLs induced by colibactin." (PMID 29559578, 2018). "Fanconi Anemia (FA) complementation group D2 protein (FANCD2) is the center of the FA tumor suppressor pathway, which has become an important field of investigation in human aging and cancer." (PMID 28157704, 2017). "FANCD2 is a pivotal molecule in the pathogenesis of Fanconi anemia (FA), an autosomal recessive human syndrome with diverse clinical phenotypes, including cancer predisposition, short stature, and hematological abnormalities." (PMID 28174693, 2017). "Fancd2 is a component of the Fanconi anemia (FA) DNA repair pathway, which is frequently found defective in human cancers." (PMID 28378742, 2017). "Suppression of FANCA and FANCD2 resulted in an increased frequency of radial chromosomal formation after treatment with mitomycin C as expected for these Fanconi anemia gene products." (PMID 28570559, 2017). "This suggests that mismatch repair pathway-coupled O6-alkylguanine-mediated DSBs during DNA replication activates the Fanconi anemia core complex and leads to the monoubiquitination of FANCD2 and FANCI." (PMID 27486975, 2016). "We also observed increased FANCA and FANCD2 (Fanconi Anemia complementation group A and D2) expression after IR; both genes being required for intra-S-phase checkpoint." (PMID 27495836, 2016). "As expected, inactivation of the Fanconi anemia pathway by FANCD2 siRNA depletion hypersensitizes cells to FA-treatment, but not CPT-treatment." (PMID 27871366, 2016). "The screen also identified the deubiquitinating enzyme USP1 (ubiquitin-specific protease 1) which deubiquitinates FANCD2, a protein involved in the Fanconi anemia DNA repair pathway." (PMID 25593194, 2015). "PD20 RV:D2 are fibroblasts derived from an individual with Fanconi Anemia subgroup D2, retroviraly complimented with a functional copy of FANCD2." (PMID 25402475, 2014). "Generally, when an ICL blocks the replication machinery, a protein complex termed as the Fanconi anemia core complex is recruited to stalled replication forks and monoubiquitinates another two Fanconi anemia proteins FANCD2 and FANCI." (PMID 24170812, 2014).
Fanconi anemia (continued). "Fanconi Anemia (FA) group D2 protein (FANCD2) is activated through monoubiquitination at K561 during DNA replication or upon DNA damage." (PMID 24658369, 2014). "Using archived and fresh glioma tissue, we show that in contrast to normal brain or benign schwannomas GBMs exhibit re-expression of FANCD2, a key protein of the Fanconi Anaemia (FA) DNA repair pathway, and possess an active FA pathway." (PMID 25071006, 2014). "A compromised Fanconi Anemia (FA) signaling pathway, often resulting from an inactivated FANCD2, was recently recognized to contribute to the development of non-FA human tumors." (PMID 23965832, 2013). "Ube2W has been shown to be responsible for the mono-ubiquitylation of BRCA1 (breast cancer early-onset 1), Fanconi's anaemia proteins FANCL (Fanconi's anaemia, complementation group L) and FANCD2 (Fanconi's anaemia, complementation group D2) and CHIP." (PMID 23560854, 2013). "In RNA-seq data, TNF receptor-associated factor 1 (TRAF1) was upregulated by 7.96 fold; CUGBP, Elav-like family member 1 (CELF1) was down-regulated by 1.16 fold; and Fanconi anemia, complementation group D2 (FANCD2) was down-regulated by 1.70 fold." (PMID 22359579, 2012). "BRCA1 has been shown to have a potential role in Fanconi anemia through its role in the colocalization of FANCD2 protein." (PMID 22761553, 2012). "For instance, upon DNA damage, the Fanconi Anemia protein FANCD2 is mono-ubiquitinated and re-localizes to the chromatin whereas ubiquitin-modified proliferating cell nuclear antigen (PCNA) recruits a specific DNA polymerase." (PMID 22347420, 2012). "The Fanconi anemia (FA) core complex promotes the tolerance/repair of DNA damage at stalled replication forks by catalyzing the monoubiquitination of FANCD2 and FANCI." (PMID 18851838, 2008). "This sensitization by phenylbutyrate correlated to a significant decrease in the formation of cisplatin-induced FANCD2 nuclear foci, which is a functional read out of the Fanconi anemia and BRCA (FA/BRCA) pathway." (PMID 18325101, 2008). "Our data demonstrate that betulinic acid suppresses the transcriptional expression of UBE2T, the E2 ubiquitin‐conjugating enzyme essential for the Fanconi anaemia (FA) core complex, thereby preventing monoubiquitination of the FANCD2‐FANCI complex and weakening FA pathway activity." (PMID 41486508, 2026). "Highlighted Article:FANCD2, a DNA damage response factor, responds to not only DNA damage but also oleic acid exposure, providing insights into the pathogenesis of lipid dysregulation in Fanconi anemia." (PMID 41065314, 2025). "Fanconi anemia complementation group D2 (FANCD2) has been reported to provide protection against formaldehyde-induced DNA damage by participating in DNA repair mechanisms, which may explain its upregulation in our study." (PMID 40428293, 2025). "Among these, Fanconi anemia group D2 (FANCD2) was one of the genes mapped to this locus." (PMID 40428293, 2025). "ssDNA exposure (RPA foci), translesion synthesis (RAD18 foci), and Fanconi Anaemia pathway activation (FANCD2) were all induced in DLD-1 WT, DLD-1 BRCA2KO, and SUM149PT cells, indicative of replication perturbation and invocation of replication fork recovery mechanisms." (PMID 41359388, 2025). "While some clinical trials have tried testing for larger lists of Fanconi anemia group genes, they have not detected any FANCD2 variants in their patients, so their value is currently unresolved." (PMID 39768544, 2024). "Protein enrichment analysis on candidate proteins that showed substantially altered abundance at replication forks in Rnf4Δ/Δ cells revealed a cluster of proteins around FANCD2, including Fanconi anemia family proteins with known functions in ensuring stable replication." (PMID 38530355, 2024).
Fanconi anemia (continued). "FANCD2 is key in the Fanconi Anemia (FA) pathway, which plays a crucial role in DNA repair." (PMID 38811536, 2024). "Moreover, 14% of the patients included in this study harbored deleterious mutations in Fanconi anemia genes (FANCA, FANCD2, FANCF, FANCG FANCI and FANCL) and in WRN, which have been reported to interact with BRCA1." (PMID 38184614, 2024). "Faap100 protein regulates Fancd2 monoubiquitination and the stability of the Fanconi anemia core complex, which could significantly affect the DNA damage response associated with Fanconi anemia." (PMID 38338077, 2024). "Additionally, the CIT effect on the total amount and phosphorylation of two cell-cycle-checkpoint proteins, the serine/threonine kinase Chk2 and Fanconi anemia (FA) group D2 (FANCD2), was determined by the cell-based ELISA." (PMID 39057961, 2024). "The replication fork protection function of FANCD2 may be distinct from its canonical roles in the Fanconi anemia pathway since different substrates may be involved." (PMID 37526271, 2023). "Additionally, we observed an 11-fold higher increment of FANCD2 foci numbers under SMG versus 1 g conditions in HSPC compared with PBL suggesting efficient fork protection from nucleases by the Fanconi anemia pathway in the immature cell type." (PMID 37762064, 2023). "This phenotype could be explained by reduced expression of several genes of the Fanconi anemia DNA repair pathway, including Fancd2, Fanci and Rad51, the promoters of which contain functionally relevant bipartite DBSs." (PMID 37661832, 2023). "Mechanically, we revealed the potential role of ZNF419 in pan-cancer from the perspective of ferroptosis, in which Fanconi anemia complementation group D2 (FANCD2) may serve as a bridge gene along with ZNF419 and ferroptosis." (PMID 36578929, 2022). "The FANCD2 (ENST00000287647.3: c.848dup) pathogenic variant was identified in a case with family history of breast, liver lung and colon cancer and has been associated to Fanconi anemia." (PMID 36428697, 2022). "In addition, a study on bone marrow damage showed that Fanconi anemia complement group D2 (FANCD2), a nuclear protein involved in DNA damage repair, can prevent iron apoptosis mediated damage in bone marrow stromal cells (BMSC)." (PMID 35559049, 2022). "FANCD2 (fanconi anemia complementation group D2), like BRCA2, may play an important role in the recombination DNA repair pathways." (PMID 36313179, 2022). "Interestingly, planispine A inhibits the Fanconi anemia pathway, as shown by reduced FANCD2 foci formation and FANCD2 monoubiquitination, which revealed the molecular mechanism of chemo-sensitization of cancer cells to cisplatin." (PMID 36364114, 2022). "Indeed, the mouse DYM homolog has a high expression in testis and has a proved interaction with FANCD2, a component of the Fanconi anemia DNA repair pathway." (PMID 33747019, 2021). "Other involved pathways were again cell cycle signaling (15%, CDK6, CDK12), Fanconi anemia/DNA repair (15%, FANCD2, NBN), and additionally peroxisome proliferator-activated receptor (PPAR) signaling (8%, PPARG) as well as discoid in domain receptor 2 signaling (8%, DDR2)." (PMID 34200508, 2021). "Interestingly, Fancd2, a member of the Fanconi Anemia proteins, was the only first-degree interacting protein identified as a hub protein in all time points." (PMID 34445425, 2021). "Double KO of POLQ and FANCD2, a DNA damage repair gene functioning in both Fanconi anemia and homologous recombination DNA damage repair pathways, significantly sabotaged cell proliferation in vitro as well as in vivo, as compared with either of these single KOs." (PMID 34206946, 2021). "Among them, cysteine dioxygenase 1 (CDO1), toll-like receptor 4 (TLR4), and dual oxidase 1 (DUOX1) were downregulated in tumors and played a protective role, while Fanconi anemia complementation group D2 (FANCD2) and others were with high expression in tumors and were risk factors for prognosis." (PMID 34820377, 2021).